MALAT1 (metastasis associated lung adenocarcinoma transcript 1)
Diseases named in the same sentence as MALAT1 in open-access papers (continued):
Sharing a sentence is not in itself a finding about the gene and the disease.
lung cancer (continued). "Significant decrease in the size of lung cancer lymph nodes and brain metastatic lung tumors was observed in patients with the GGGT genotype in MALAT1 when compared to patients with CACC, CGCC, CAGC, GAGT and CACT genotypes." (PMID 36934373, 2023). "For example, lung cancer tissues exhibit elevated levels of HOTAIR and MALAT1, which can facilitate the growth, invasion, and metastasis of lung cancer." (PMID 38011277, 2023). "A signaling pathway of MALAT1/miR-328/KATNB1 was established to explain the down-regulation of KATNB1 mRNA in patients carrying haplotype GGGT and reduced lymph node size in lung cancer and tumor size in brain metastatic lung cancer." (PMID 36934373, 2023). "MALAT1 also regulates the suppression of immune responses to tumors and other pathological conditions by controlling MDSC-mediated lung cancer suppression." (PMID 36419933, 2022). "MALAT1 activates the epithelial-mesenchymal (EMT) process and increases brain metastasis-initiating lung cancer cells." (PMID 35454102, 2022). "The current work sought to provide novel insights into the functional response of MALAT1 and efficacy of common members of SLs (ALT and Brv-A) in paclitaxel-resistant lung cancer, vis-à-vis MALAT1/STAT3 and MALAT1/FUT4 axis." (PMID 35281907, 2022). "In this study, we explored the positive correlation of MALAT1 with STAT3 and FUT4 activity in paclitaxel resistant A549 (A549/T) lung cancer cells." (PMID 35281907, 2022). "In the context of lung cancer, it has been recently demonstrated that OCT4, a key stemness transcription factor, promotes NEAT1 and MALAT1 transcription by targeting their promoter and enhancer regions." (PMID 35814429, 2022). "In lung cancer cells, overexpression of OCT4 upregulated the transcriptional activity of the NEAT1 promoter and MALAT1 enhancer, as well as their expression." (PMID 35907897, 2022). "For example, inhibiting MALAT1 with ASO suppresses metastasis in mice bearing breast cancer and in lung cancer xenograft models." (PMID 33804511, 2021). "Many lncRNAs have been reported to play key roles in promoting lung cancer cell migration both in vivo and in vitro, including UPAT, ENST457720, HOXD-AS1, and MALAT1." (PMID 33809929, 2021). "Although they were on the top of the list, long non-coding RNAs (LncRNAs) MALAT1 and NEAT1 have already been characterized as the hallmarks of metastasis in lung cancer and other malignant tumors." (PMID 33144684, 2021). "Research has shown that the expression of HOTAIR, MALAT1, HOTTIP, ANRIL, and ZXF2 were upregulated in lung cancer tissues, which is related to increased tumor lymph node metastasis rate, advanced lymph node metastasis, and decreased overall survival." (PMID 33627711, 2021). "This study explored the ceRNA regulatory mechanism of the MALAT1/miR-491-5p/UBE2C system, providing a potential therapeutic target for lung carcinoma." (PMID 34257576, 2021). "For example, the lncRNAs MALAT1 and NEAT1 play important roles in lung cancer cell proliferation, cell cycle progression, and apoptosis, as well as tumor progression and prognosis." (PMID 32819367, 2020). "Several lncRNAs such as H19, MALAT1, and DANCR act as oncogenes in lung cancer by interacting with miRNAs." (PMID 33412752, 2020). "At present, research on 1ncRNAs in cisplatin resistance in lung cancer was still in its infancy, and some lncRNA molecules related to cisplatin resistance in lung cancer had been screened and identified, including H19, XIST, SFTA1P, CCAT1, and MALAT1." (PMID 32626737, 2020). "In lung cancer cells, NEAT1 and MALAT1 have been proved to be downstream effectors of Oct4-induced lung cancer proliferation, migration and invasion." (PMID 33298086, 2020). "Evidently, MALAT1, HOTAIRM1, and RUNXOR regulate important biological activities (e.g., expansion, differentiation, and immunosuppressive functions) of MDSCs in lung cancer." (PMID 31404149, 2019).
lung cancer (continued). "Thus, MALAT1 could negatively regulate the differentiation of MDSCs in patients with lung cancer." (PMID 31404149, 2019). "The lncRNA MALAT1, also known as nuclear-enriched transcript 2 (NEAT2), was initially discovered as a promising biomarker for lung cancer metastasis." (PMID 30127741, 2018). "Flow cytometry analysis showed that MALAT1 knockdown increased cisplatin-induced apoptosis in A549, A549/DDP and H1299 lung cancer cell lines than in corresponding controls." (PMID 29484127, 2018). "We showed that lung cancer cells overexpressing NEAT1 or MALAT1 and the Oct4-silenced cells reconstituted with NEAT1 or MALAT1 promoted cell proliferation, migration and invasion." (PMID 28615056, 2017). "Subsequently, enhanced MALAT1 expression promotes SOX9 expression, so as to enhance the chemo-resistance of lung cancer cell to DDP." (PMID 29212230, 2017). "Then these si-MALAT1-transfected A549 and H1299 cells were exposed to DDP treatment (1, 2, 4, 6, 8, 16, 32 μg/ml) to validate the inhibitory effect of DDP on lung cancer cell viability." (PMID 29212230, 2017). "In the differentially expressed lncRNAs, BANCR, kucg 1, MALAT1, NEAT1 were chosen for further study in lung cancer." (PMID 28938549, 2017). "MALAT1 (also known as NEAT2), as the first identified lncRNA in lung cancer, is well studied in recent decades." (PMID 28415568, 2017). "These clinical studies clearly indicated that Oct4 positively correlates with NEAT1 and MALAT1 expression in lung cancer and that Oct4/NEAT1/MALAT1 co-overexpression is an independent factor for prediction of poor outcome in lung cancer patients." (PMID 28615056, 2017). "In this study, MALAT1, miR-101 and SOX9 formed a feedback loop, which plays a crucial role in regulating the chemo-resistance of lung cancer cell through activation of chemo-resistance-related Wnt signaling pathway." (PMID 29212230, 2017). "Since oncogenic lncRNAs, NEAT1 and MALAT1, were positively regulated by Oct4 at transcriptional level, we further characterized the oncogenic roles of NEAT1 and MALAT1 lncRNAs in lung cancer cells." (PMID 28615056, 2017). "Using the same method, the expression of lncRNAs MALAT1, BANCR, NEAT1 in primary lung cancer were also analyzed." (PMID 28938549, 2017). "In the present study, we demonstrated the interaction between MALAT1 and miR-101, between miR-101 and SOX9, a direct downstream target of miR-101, in lung cancer cells through RNA immunoprecipitation and Luciferase assays." (PMID 29212230, 2017). "Our findings provide a novel understanding of the role of MALAT1 and this MALAT1-miR-101-SOX9 feedback loop in lung cancer chemo-resistance and the mechanism involved." (PMID 29212230, 2017). "Here, we further investigated the interaction between MALAT1 and miR-101, miR-101 and SOX9 in lung cancer cells using RNA immunoprecipitation assays with the AGO2 antibody." (PMID 29212230, 2017). "To further validate Oct4/NEAT1 and Oct4/MALAT1 transcriptional axes in lung cancer patients, we examined RNA expression level of Oct4, NEAT1 and MALAT1 using qRT-PCR analysis of samples from 124 lung cancer patients." (PMID 28615056, 2017). "To date, only a few lncRNAs (including MALAT1, HOTAIR, H19, MEG3, GAS5, ANRIL, and SOX2OT etc.)have been reported to be dysregulated and functionally characterized in lung cancer and most of the studies were based on microarray expression data." (PMID 26862852, 2016). "While lncRNAs in lung cancer is still an emerging field, several have been shown to be involved in tumorigenesis, including HOTAIR, H19, ANRIL, and MALAT1." (PMID 22852089, 2012). "Nude rodents that were administered MALAT-1 ASO systemically exhibited significantly lower lung cancer cell colonization from patients than non-targeting controls." (PMID 39912974, 2025).
lung cancer (continued). "Concordantly, our recently published Non-Small Cell Lung Cancer (NSCLC) scRNA-seq atlas revealed that MALAT1 and NEAT1 are highly abundant in various cells of the lung cancer TME and noticeable higher expressed in datasets generated with 10X Chromium compared to BD Rhapsody, respectively." (PMID 38689972, 2024). "Notably, a significant correlation was found between MALAT1 and MCP-1 levels in the plasma of lung cancer patients from the AA population (r = 0.935, p = 0.001), a correlation not observed in the WA population (r = 0.229, p = 0.096)." (PMID 38791954, 2024). "MALAT1 and HOTAIR are found expression in various tumors, including lung cancer." (PMID 38270295, 2024). "Although the expression levels of MALAT1, HOTAIR, and AFAP1‐AS1 showed a statistically significant correlation with LNM in lung cancer patients according to the forest plots, the quality assessment tests demonstrated that the outcome for AFAP1‐AS1 is more reliable." (PMID 39725668, 2024). "The findings suggest that MALAT1 may regulate MCP-1 expression and enhance malignant behaviors, while its knockdown significantly reduces these characteristics in lung cancer cells." (PMID 38791954, 2024). "Furthermore, we present a paradigm in MALAT1 expression: MALAT1 is reported to regulate MAPK-signaling and promote oncogenic functions in melanoma, liver, and lung cancer." (PMID 37235843, 2023). "The lncRNA metastasis-associated lung adenocarcinoma transcript 1 (MALAT1), as the name indicates, was first identified in non-small cell lung cancer (NSCLC) and in association with lung cancer metastasis." (PMID 37569483, 2023). "In radiotherapy, MALAT1 also promotes resistance, although this function has not been explored in lung cancer." (PMID 37370745, 2023). "The expression of MALAT1 was found to be stronger in the whole blood of lung cancer patients with metastasis compared to those without metastasis." (PMID 37250901, 2023). "While additional lung-cancer-focused studies are lacking, the MALAT1 role in cisplatin resistance was also found in a xenograft model of oral squamous cell carcinoma." (PMID 37370745, 2023). "MALAT1 has a well-established role in lung cancer progression and carcinogenesis, but further research will be required to uncover common links between its mechanisms of action in COPD and lung cancer." (PMID 36769181, 2023). "Increasingly investigations showed that MALAT1 was not only a reliable metastasis-related biomarker but also a vital regulator involved in occurrence, invasiveness, drug resistance, and metastasis of various cancers such as HCC and lung cancer." (PMID 36685103, 2022). "Indeed, the comparative analysis of whole blood samples from 105 lung cancer patients and 65 healthy subjects revealed a decrease in blood MALAT-1 levels in cancer patients, while lung cancer tissues showed higher MALAT1 expression." (PMID 35729321, 2022). "Furthermore, NEAT1 and MALAT1 function as downstream mediators of OCT4 to promote proliferation, migration and invasion of lung cancer cells." (PMID 35814429, 2022). "Furthermore, these two natural SLs suppressed MALAT1 expression, STAT3 activation, and FUT4 and P-GP expression which are the hallmarks for paclitaxel resistance in A549 lung cancer cells." (PMID 35281907, 2022). "Similar to that of lncRNAs, such MALAT1, the miRNA sponging function of LINC00958 localized in the cytoplasm may promote lung cancer progression." (PMID 35223488, 2022). "In a xenograft lung cancer metastasis model, ASO blocking MALAT1 can markedly reduce metastasis; thus, silencing MALAT1 may be an appropriate therapeutic target, and MALAT1 can be therapeutically targeted by ASO and siRNA." (PMID 35819532, 2022). "One unsolved issue is notably the reported lack of correlation between the levels of circulating MALAT-1 in lung cancer patients and the levels of this lncRNA in lung cancer tissues." (PMID 35729321, 2022).
lung cancer (continued). "Some LncRNAs including HOTAIR, MALAT1, NEAT1, and NNT‐AS1 have been involved in cisplatin resistance, through WNT and/or MAPK/Slug intracellular signaling pathways, as well as promoting malignancy in solid lung tumors, and lung cancer cell lines." (PMID 33433063, 2021). "Similar to other blood‐based tumor markers, some lncRNAs are not very sensitive in the diagnosis of lung cancer, such as MALAT1." (PMID 33931980, 2021). "MALAT1 and NEAT1 have been widely studied non-coding RNAs, and some studies have demonstrated that they have clear correlations with various cancers such as hepatocellular carcinoma and lung cancer." (PMID 33499813, 2021). "Their results indicated a negative link between the MALAT1 level and the MDSCs proportion in PBMCs of lung cancer patients." (PMID 33133086, 2020). "In conclusion, we demonstrate that higher MALAT1 expression is a negative prognostic biomarker in lung cancer and indicates cisplatin resistance." (PMID 29484127, 2018). "Moreover, MALAT1 levels were higher in the cisplatin-resistant A549/DDP cell line than in cisplatin-sensitive A549, H460, H1299 and SPC-A1 lung cancer cell lines." (PMID 29484127, 2018). "There was positive correlation between MALAT1 and MCL1 mRNA expression in lung cancer tissues." (PMID 29484127, 2018). "Subsequent cell viability assays performed on DDP-resistant lung cancer cells (A549/DDP and H1299/DDP) showed that MALAT1 knockdown reduced the lC50 values for both A549/DDP and H1299/DDP cells, indicating MALAT1 knockdown sensitizes DDP-resistant lung cancer cells to DDP." (PMID 29212230, 2017). "Unlike the low expression of MALAT1 in the whole blood of lung cancer patients, the expression of MALAT1 derived miniRNA (MD miniRNA) was elevated in plasma of PCa patients, which was consistent with MALAT1 expression in PCa tissues." (PMID 27143813, 2016). "But one common thing in tissues and whole blood was that metastatic lung cancer patients had stronger expression of MALAT1 than nonmetastatic lung cancer patients." (PMID 27143813, 2016). "Shen L reported that MALAT1 could be used as predictor of NSCLC brain metastasis and outcome and MALAT1 promoted brain metastasis of lung cancer by inducing EMT in H1915 cells." (PMID 26522444, 2015). "Using these MALAT1-knockout cells, the authors demonstrated that MALAT1 represses anti-metastatic genes and activates pro-metastatic genes in lung cancer cells, but does not affect genes regulating cell growth." (PMID 24013378, 2013). "MALAT1 can interact with the histone methyltransferase EZH2, promoting the methylation of histone H3K27 in the promoter regions of certain tumor suppressor genes, inhibiting the expression of these genes and promoting the invasion and metastasis of lung cancer cells." (PMID 41394878, 2025). "In xenograft models of lung cancer and epidermal carcinoma cell lines A549, A431, PC9GR, and PC9, Cy5.5-labeled ASOs exhibit evident binding specificity and discernible imaging effect in both in vitro and in vivo, effectively reflecting MALAT1 expression levels in tumors." (PMID 40597438, 2025). "Interestingly, the H513, H1373, and H1385 lung cancer cell lines, originating from an AA patient, exhibited a higher level of MALAT1 and MCP-1 levels in both cells and their supernatants compared to the other three cell lines (A549, H460, and H520) developed from WA lung cancer patients." (PMID 38791954, 2024). "Interestingly, MALAT1 and Nuclear Paraspeckle Assembly Transcript 1 (NEAT1) are also transcriptionally regulated by OCT3/4, with evidence that OCT3/4 binds to the promoter of MALAT1 while acting as an enhancer for NEAT1, thereby increasing their expression in lung cancer." (PMID 39062685, 2024). "Notably, while numerous studies have documented the oncogenic function of MALAT1 in various tumors, its specific role in lung cancer among AAs had not been previously investigated." (PMID 38791954, 2024).
lung cancer (continued). "A signaling pathway of MALAT1/miR-328/KATNB1 was established in our study, which explained the down-regulated KATNB1 mRNA and katanin P80 levels in patients carrying haplotype GGGT and reduced lymph node size in lung cancer and tumor size in brain metastatic lung cancer." (PMID 36934373, 2023). "Hence, we hypothesized that MALAT1 might act as a ceRNA for sponging miR-491-5p and controlling UBE2C expression to regulate the progression in a substantial number lung carcinoma." (PMID 34257576, 2021). "The mechanism of MALAT1 in lung carcinoma development is not understood very well." (PMID 34257576, 2021). "In spite of the acknowledged role of MALAT1 in the pathogenesis of lung cancer, we could not find any significant difference in expression of this lncRNA between lung cancer tissues and ANCTs." (PMID 32514489, 2020). "Additionally, MALAT1 expression was significantly higher in patients with brain metastasis from lung cancer when compared to patients without brain metastasis." (PMID 33371204, 2020). "Similarly, MALAT1, UCA1, ANRIL, and NEAT1 were shown to predict lung cancers." (PMID 31141943, 2019). "Again one of them is MALAT1, which has been shown to be an active player in lung cancer metastasis, and targeting MALAT1 by ASO drastically reduced metastasis formation of this tumor cells in vivo, suggesting the use of an ASO against lncRNA in lung cancer therapy." (PMID 29755696, 2018). "Taken together, MALAT1, miR-101 and SOX9 form a feedback loop to enhance the chemo-resistance of lung cancer cell to DDP; this MALAT1-miR-101-SOX9 feedback loop plays an important role in the chemo-resistance of lung cancer cell to DDP and may serve as a potential target for cancer treatment." (PMID 29212230, 2017). "Since the lncRNA, MALAT1, was upregulated in solid tumor tissue compared with the corresponding normal tissue, we investigated whether EPB41L4A-AS2 expression had a similar expression pattern in both renal cancer and lung cancer." (PMID 26980733, 2016). "As stable MALAT1 knockout in lung cancer cells up-regulates HTR2B expression and silencing of HTR2B is a marker for ovarian tumor metastasis in ovarian cancer patients, we propose that repression of HTR2B expression contributes to MALAT1-mediated tumor cell migration, invasion and metastasis." (PMID 24742640, 2014). "However, its capacity for regulating alternative splicing could not be confirmed in MALAT1 knockout mice or lung cancer cells." (PMID 26420912, 2015). "Increased MALAT1 is also seen in NSCLC patients with brain metastasis compared to those without, providing further support for its role in lung cancer metastasis." (PMID 33803619, 2021). "Several studies are previously conducted to discover the role of lncRNA MALAT1 in chemoresistance, however, how MALAT1 functions in the context of a therapeutic approach with special prominence to MALAT1/STAT3 and MALAT1/FUT4 axis in paclitaxel-resistant lung cancer is not well-known." (PMID 35281907, 2022). "Upregulated XIST, MALAT1, and NEAT1 lncRNAs were predicted to modulate and promote cell development and further metastasis in multiple cancers through mir-124-3p, but no studies in lung cancer were done regarding other functions of these lncRNAs, or their response to VRB." (PMID 38137519, 2023).